SPACA6 (sperm acrosome associated 6)
Description:
Sperm protein required for fusion of sperm with the egg membrane during fertilization (By similarity). May regulate the expression of sperm surface protein DCST2 (By similarity).
Synonyms: SPACA6P; LET7EH; LINC00085; NCRNA00085
Tractability: Antibody: its Gene Ontology location is reachable by antibodies, with high confidence; UniProt predicts a signal peptide or a membrane-spanning region.
Gene: Protein-coding gene on chromosome 19 (51,688,346 to 51,712,387, forward strand). Ensembl gene ENSG00000182310.
Subcellular location: Cytoplasmic vesicle, secretory vesicle, acrosome membrane
Gene Ontology:
Molecular function: protein binding; protein-macromolecule adaptor activity
Biological process: sperm-egg recognition; fusion of sperm to egg plasma membrane involved in single fertilization
Cellular component: plasma membrane; acrosomal membrane; acrosomal vesicle
Homologues: Orthologues: chimpanzee SPACA6 (99% identical), macaque SPACA6 (96% identical), pig SPACA6 (78% identical), dog SPACA6 (71% identical), guinea pig SPACA6 (67% identical), mouse Spaca6 (64% identical), rat Spaca6 (54% identical).
Diseases named in the same sentence as SPACA6 in open-access papers:
SPACA6 is named in the same sentence as 10 diseases in open-access papers, as found by Europe PMC text mining. Sharing a sentence is not in itself a finding about the gene and the disease. The quoted sentences say what the papers report.
Infertility (6 papers, 2020 to 2024). "The random mutation harboured by these infertile males consists of a large insertion that introduced an 11 kb deletion disrupting Spaca6 gene expression." (PMID 32484434, 2020). "The ultimate evidence that SPACA6 is essential for human fertilization would be to find a few familial cases or several infertile isolated patients with a mutation in the SPACA6 gene." (PMID 32210282, 2020). "The authors of the other study identify a strong down-regulation of SPACA6 in the sperm of Frey-deficient mice, which might represent an explanation for the infertility of these mice." (PMID 35960805, 2022). "Eight genes that result in male infertility (IZUMO1, SPACA6, TMEM95, TMEM81, SOF1, FIMP, DCST1, and DCST2) and an additional two that cause infertility in females (JUNO and CD9) have been identified." (PMID 38381819, 2024). "In the interest of better understanding the fundamental processes behind human sperm-egg fusion – thereby informing future advances in both family planning and infertility treatment – we undertook structural and biochemical studies of SPACA6." (PMID 36115925, 2022). "Phenotypic analyses were carried out to investigate whether the infertility of Spaca6 del/del males was derived from abnormalities in the male reproductive system." (PMID 32393636, 2020). "Despite the strong structural similarity between SPACA6 and IZUMO1, knockouts of genes encoding either protein alone results in infertility of male mice, indicating that they are not redundant in their functions in gamete fusion." (PMID 36115925, 2022).
male infertility (3 papers, 2019 to 2024). The inability of the male to effect fertilization of an ovum after a specified period of unprotected intercourse. "Further studies are needed to examine the cause of male infertility in Fimp KO mice and to clarify the interaction of IZUMO1, SPACA6, and FIMP." (PMID 32295885, 2020). "However, some defects are not detectable through conventional tests because deficiencies of the essential acrosomal proteins such as IZUMO1 or SPACA6 cause serious male infertility in mice without causing morphological or motility change in spermatozoa." (PMID 31569716, 2019).
alcoholic hepatitis (1 paper, 2019). Acute hepatitis resulting from ingestion of alcohol. "Spaca6, or sperm acrosome associated protein 6, has not previously been implicated in alcoholic hepatitis or the immune system, even though the miRNAs clustered within Spaca6 have known roles in the immune system." (PMID 31231396, 2019).
esophageal squamous cell carcinoma (1 paper, 2025). Esophageal squamous cell carcinoma (ESCC) is a type of esophageal carcinoma (EC) that can affect any part of the esophagus, but is usually located in the upper or middle third. "Concomitant with the upregulation of SPACA6 levels, elevated expression of the miR-99b∼125a∼let-7e cluster was reported in liver cancer and esophageal squamous cell carcinomas, where it promoted tumor invasion and metastasis through regulation of ZEB1 activity." (PMID 41550951, 2025).
glioma (1 paper, 2022). A benign or malignant brain and spinal cord tumor that arises from glial cells (astrocytes, oligodendrocytes, ependymal cells). "We further discovered that GAS5 inhibited the viability of glioma cells through miR-let-7e and miR-125a by protecting SPACA6 from degradation." (PMID 36106122, 2022).
melanoma (1 paper, 2025). A malignant, usually aggressive tumor composed of atypical, neoplastic melanocytes. "In conclusion, our study uncovers the critical role of the SPACA6-hosted miR-99b~125a~let-7e cluster in sustaining BRAF/MEKi resistance in melanoma." (PMID 41550951, 2025). "We observed elevated SPACA6 expression levels in melanoma tumors that progressed during BRAF/MEKi therapy, an increase associated to the upregulation of the hosted miR-99b∼125a∼let-7e cluster." (PMID 41550951, 2025). "Here, we uncovered a role for SPACA6-hosted miR99b~125a~let-7e cluster in sustaining BRAF/MEKi resistance in melanoma tumors and cell lines." (PMID 41550951, 2025). "In this study, we report for the first time that the SPACA6-hosted miR-99b~125a~let-7e cluster contributes to melanoma cell and tumor resistance to BRAF/MEKi through a mechanism involving the mTOR signaling pathway." (PMID 41550951, 2025).
sterility (1 paper, 2020). "There are two important points in common between the three genes described as essential to gamete adhesion/fusion and Spaca6: sterility of KO male mice for Izumo11 and female KO mice for Cd93–5 and Juno2, and the presence of sperm in the PVS." (PMID 32210282, 2020).
tumor (3 papers, 2020 to 2025). "Beyond the association of SPACA6-hosted miRNA cluster with tumor progression, we detected a positive correlation between SPACA6, miR-99b, miR-125a and let-7e with key immunosuppressive factors such as TGFβ and CCL2, suggesting a potential role in sustaining an immunosuppressive TME." (PMID 41550951, 2025). "Together, these findings identify the SPACA6-hosted miR-99b~125a~let-7e cluster as a regulator of BRAF/MEK inhibitor resistance through promotion of tumor survival and of an immunosuppressive microenvironment." (PMID 41550951, 2025).
cancer (2 papers, 2024 to 2025). A tumor composed of atypical neoplastic, often pleomorphic cells that invade other tissues. "While SPACA6 has been assigned a role in gamete binding and fusion, miR-99b, miR-125a and let-7e were reported to regulate inflammatory immune responses and to be involved in autoimmune disease and cancer biology." (PMID 41550951, 2025). "CHST2, SPACA6, and TSC22D1 had lower methylation levels in cancer tissues than Riplet and GNB4, in which CHST2 and TSC22D1 had higher methylation levels in normal tissues." (PMID 38154055, 2024). "SPACA6 gene is not recognized as a cancer driver, although its expression has been detected in multiple cancer types." (PMID 41550951, 2025).
SPACA6 also shares sentences with these, for which no sentence is quoted: liver cancer (1 paper).